PRAME (PRAME nuclear receptor transcriptional regulator)
Diseases named in the same sentence as PRAME in open-access papers (continued):
Sharing a sentence is not in itself a finding about the gene and the disease.
tumor (continued). "Conversely, GNA11 mutations were associated with Class 2 tumors (p = 0.0005), PRAME(+) status (p = 0.05), increased patient age (p = 0.002), increased tumor diameter (p = 0.004) and tumor thickness (p = 0.002), and they showed a near-significant association with ciliary body involvement (p = 0.06)." (PMID 41387680, 2025). "Ectopic PRAME expression has been reported in several types of cancer, where it has been associated with poor prognoses and aggressive disease, including invasive disease and accelerated tumor growth." (PMID 40101298, 2025). "Finally, PRAME was linked to the control of many signaling pathways implicated in tumor immunity and tumorigenicity, according to GSEA analysis." (PMID 40004764, 2025). "In addition, the study, which included over 5800 tumour cases, characterised PRAME as a relatively unspecific marker, limiting its diagnostic utility in surgical pathology." (PMID 38338862, 2024). "Additionally, the MSAB partially inhibited the tumor growth-promoting effect in vivo that was caused by PRAME overexpression." (PMID 36980687, 2023). "Nine articles investigated the associations between PRAME expression and tumour stage." (PMID 33381588, 2020). "In addition to supporting tumor cell features, PRAME has been implicated in the regulation of the immune response." (PMID 31311081, 2019). "Interestingly, PRAME+ status was statistically associated with a larger tumour diameter after analysing the TCGA (The Cancer Genome Atlas Research Network dataset)." (PMID 31109147, 2019). "Additionally, in a number of malignancies, PRAME expression levels were closely associated with immunological neoantigens, immune infiltration, immune score, immune checkpoint, tumor mutation burden, microsatellite instability, mismatch repair, and DNA methyltransferase." (PMID 40004764, 2025). "Collectively, these data indicate that PRAME is well expressed in a diversity of tumors exhibiting oncogenic mutations or cellular and molecular features associated with sensitivity or resistance to immune checkpoint inhibitors, e.g. tumor mutation burden or immune infiltration." (PMID 39659431, 2024). "Hence, aberrant expression of PRAME may predispose tumor cells to isochromosome formation, as well as other forms of aneuploidy that promote tumor progression." (PMID 27486988, 2016). "In addition to tumor development, PRAME is implicated in germ cell development." (PMID 21347312, 2011). "PRAME expression in cancers may therefore be due to reactivation of genes associated with 'stemness' or pluripotency, or in response to signals that activate immune or autoimmune responses associated with tumours." (PMID 20799951, 2010). "Both AEI and AI were measured in a series of informative patients using mRNA-encoded cSNPs for SERPINB5 (encoding maspin), TERT (encoding a telomerase subunit) and PRAME (encoding a tumour antigen of unknown function with a highly restricted normal tissue expression pattern." (PMID 16222316, 2005). "Although expressed in several tumor types, PRAME was found to be the most upregulated gene in pituitary blastoma, a tumor that is part of the DICER1-associated tumor spectrum." (PMID 40448797, 2025). "This suggests that at least two CTAs—LDHC and PRAME – play vital roles in tumor development and progression by regulating anti-tumor immune responses." (PMID 40108668, 2025). "In our previous work, we demonstrated that aberrant expression of PReferentially expressed Antigen in Melanoma (PRAME) in tumor cells contributes to dampening the adaptive immune response." (PMID 40108668, 2025). "PRAME’s tumor-specific expression makes it a promising biomarker, opening up promising possibilities across multiple clinical domains, from diagnosis to prognosis and therapy." (PMID 40868240, 2025). "MDG1011-mediated cytotoxicity of tumor cells was determined using Mel624.38 target cells that co-express natural levels of HLA-A2 and endogenous intracellular PRAME proteins." (PMID 39858024, 2025).
tumor (continued). "The findings emphasize the value of incorporating multiple biomarkers, such as PRAME or p16, into routine clinical practice to better predict tumor behavior and guide therapeutic decisions." (PMID 41155720, 2025). "When compared with S100 and SOX10, PRAME was demonstrated to be less sensitive but much more specific because of its limited expression in benign melanocytic lesions." (PMID 40507250, 2025). "Immunohistochemically, the tumor cells were diffusely positive for PRAME and SOX10, focally positive for Melan-A, and very focally positive for HMB45." (PMID 40437181, 2025). "In myxoid liposarcomas, PRAME expression was detected in 90% of cases, correlating with higher tumor grade and advanced clinical stage." (PMID 40868240, 2025). "Collectively, our data demonstrate that the PRAME-targeting ImmTAC® can redirect T cells to selectively and efficiently kill PRAME+/HLA-A*02:01+ tumor cells with varying levels of PRAME expression and peptide presentation." (PMID 39659431, 2024). "Ongoing efforts to optimise the design of immunotherapeutic strategies and to understand the intricate interplay between the tumour microenvironment and PRAME expression are essential for translating the potential of PRAME into clinical success." (PMID 38338862, 2024). "Here we show that PRAME is expressed homogenously and at high frequency across multiple tumor indications, in primary and metastatic lesions." (PMID 39659431, 2024). "Given that PRAME is upregulated in various types of neoplasia, it would be interesting to understand how different factors work together to regulate PRAME expression." (PMID 38338862, 2024). "It targets PRAME (Preferentially Expressed Antigen in Melanoma) while also pulling T-cells to the tumor directly." (PMID 39451258, 2024). "For instance, the targeting of CTAs such as NY-ESO-1 and PRAME has shown notable pre-clinical anti-tumor activity and is currently undergoing evaluation in clinical trials using vaccine-based or adoptive cell therapy." (PMID 39001513, 2024). "The variability of PRAME expression among different tumours, the understanding of its precise role in tumour biology, and the optimisation of immunotherapeutic strategies to target PRAME are areas of active research." (PMID 38338862, 2024). "This is a plausible explanation for the high expression of PRAME in tumor cells with highly proliferative phenotypes." (PMID 39451258, 2024). "SOX10 and PRAME resulted positive in all tumor cells, whereas the other melanocytic markers showed extreme heterogeneity." (PMID 38191367, 2024). "The mRNA expression pattern was in line with tumor data showing high PRAME expression in SS compared to other STS." (PMID 39550391, 2024). "In recent years, multiple CTAs, including PRAME, have been evaluated as potential targets for immunotherapy as they are selectively presented on the HLA-1 surface proteins of tumor cells." (PMID 39451258, 2024). "utilized small interfering RNAs (siRNAs) to knock down PRAME in the K562 cell line, and tumor inhibition and growth were observed in vitro and in vivo, respectively Consequently, more studies are needed to further elucidate the opposing conclusions." (PMID 38596687, 2024). "The third understood role of PRAME in tumorigenesis is in its promotion of a pro-tumor microenvironment by increasing tumor “coldness”." (PMID 39451258, 2024). "The staining for PRAME in BCCs and SCCs was heterogeneous, with variable staining intensity among different tumor cells within the same lesion." (PMID 39727621, 2024). "PRAME (Preferentially expressed Antigen in Melanoma) is a cancer–testis antigen expressed in several tumor indications, representing an attractive anticancer target." (PMID 39659431, 2024). "To further investigate the ability of IMC-F106C to redirect T cells to selectively kill PRAME+/HLA-A*02:01+ tumor cells, we developed an organoid model from either PRAME+ or PRAME– tumors." (PMID 39659431, 2024).
tumor (continued). "Given the broad and high PRAME expression in many tumor types, we expect the PRAME TCRs to be valuable for treatment of other PRAME positive tumors as well." (PMID 37026005, 2023). "In conclusion, these data suggest that expression of PRAME is linked to Axl in HCC patients, favoring tumor progression as indicated by the correlation with advanced stages, increased invasion and a poorer survival probability of HCC patients." (PMID 37173882, 2023). "Bioinformatic analysis in the TCGA-BRCA cohort also confirmed that PRAME was upregulated in tumor tissues compare with normal tissues." (PMID 38022619, 2023). "In particular, PRAME is involved in many cellular processes that are relevant for tumor genesis, such as proliferation, anti-apoptosis and metastasis." (PMID 37047361, 2023). "Specifically, expression levels of BCL2, SLC40A1, and TFF1 were decreased in BCa samples with respect to normal tissues, whereas APOOL and PRAME were increased in tumor samples." (PMID 37728703, 2023). "The PRAME expression in tumor tissues was higher than that in adjacent normal cervical tissues, and it was localized mainly in the nucleus." (PMID 36980687, 2023). "This study provides insights into the molecular aspects of Axl-driven HCC progression and identified the CTA PRAME as a tumor-promoting target gene of Axl." (PMID 37173882, 2023). "In conclusion, these data provide evidence that PRAME is tumor-promoting because it positively influences proliferation and clonogenicity." (PMID 37173882, 2023). "Interactions with pro-oncogenic proteins such as CCAR1 suggested further tumor-promoting functions of PRAME in HCC." (PMID 37173882, 2023). "Concerning our patients, in case 1, the tumor showed a dominant vertical growing pattern, while case 2 harbored a horizontal growing phase, but in both cases, the tumor cells showed a diffuse and strong PRAME positivity." (PMID 37898793, 2023). "PRAME expression was analyzed in 57 pairs of LSCC tumor tissue samples through quantitative real-time PCR, and the correlation between PRAME and clinicopathological features was analyzed." (PMID 36910848, 2023). "The tumor weight of the stable transfection with the overexpressed PRAME group was significantly higher than that in other three groups." (PMID 36910848, 2023). "In 57 tumor tissues, the P values revealed the correlation between a high expression level of PRAME and the TNM staging (P < 0.05), as well as with lymphatic metastasis (P < 0.05)." (PMID 36910848, 2023). "The comparison of the mRNA expression levels of 32 genes of the 21 CTAs between relatively healthy and tumor ovarian tissue showed up-regulation in the expression level of the AKAP3, MAGEA4, PIWIL1, and PRAME genes in tumor samples." (PMID 37835834, 2023). "Further, the patient is PRAME positive, suggesting this patient has three risk factors for poor prognosis despite being GEP1 from tumor biopsy." (PMID 37047796, 2023). "PRAME plays an important role in tumor biology and has been identified as a biomarker for Class 1 UM." (PMID 37626310, 2023). "Further, PRAME is involved in many cellular processes that are relevant for tumor genesis, such as proliferation, anti-apoptosis and metastasis formation." (PMID 37047361, 2023). "Immunophenotyping revealed consistent negativity for the melanocytic markers MART-1 and HMB-45, while S100, SOX-10 and PRAME showed nuclear positivity in all tumor parts including the dedifferentiated area." (PMID 35645230, 2022). "The significance of focal PRAME positivity in benign melanocytic lesions is still unclear, which necessitate further studies to determine the potential risk of malignant transformation related to focal PRAME positivity." (PMID 35484605, 2022). "All KC tumors, with the exception of one poorly-differentiated SCC, exhibited PRAME expression in 1–24% of tumor cells." (PMID 35892887, 2022). "Notwithstanding, PRAME expression can appear at any stage of tumor progression and not only in advanced stages." (PMID 35328098, 2022).
tumor (continued). "Differences among the four TCRs were most obvious after co-culture with the tumor cell line MelA375 that expressed only low levels of PRAME mRNA, whereby only TCR-Ts with TCR-027-004 released substantial amounts of IFN-γ." (PMID 35454906, 2022). "The multiplex ddPCR assay was developed using tumor cell lines positive for the tumor associated antigens (TAA: WT1, PRAME, BIRC5), with homeostatic ABL1." (PMID 36248870, 2022). "As a second step in this setting, tumors escape T cell detection by deletion of the PRAME gene locus with PRAME-deleted tumor cells, thus avoiding cytotoxic T cell attack." (PMID 35380993, 2022). "HLA-A*02:01-positive tumor cell lines with varying levels of PRAME mRNA and derived from different indications were used as target cells to analyze the effector functions of the two TCR-T populations in vitro." (PMID 35454906, 2022). "In several types of cancer, PRAME expression correlates with aggressive disease characteristics, including high tumor grade, high proliferative index and metastatic propensity." (PMID 35892887, 2022). "Together, our data indicate that targeting of PRAME offers a potential, novel dual therapeutic approach to specifically target tumour cells and regulate immune activation in the tumour microenvironment." (PMID 34612587, 2021). "The function of PRAME in normal and tumor cells is not completely understood, although a role in the regulation of retinoic acid signaling and immune evasion has been proposed." (PMID 35076507, 2021). "As such, it would be of interest to further study the effect of PRAME tumour expression on other immune checkpoints such as TIM‐3 and LAG‐3 within the context of immune checkpoint blockade." (PMID 34612587, 2021). "The restricted, highly tumour‐specific expression of PRAME in conjunction with its oncogenic functions support the rationale for therapeutic targeting of PRAME in cancer." (PMID 34612587, 2021). "PRAME expression tended to be more frequent in tumours with low numbers of TILs (9/56, 16.1%) than in tumours with high TIL counts (16/193, 8.3%, p = 0.126)." (PMID 33287125, 2020). "In the present study, we provide experimental evidence that PRAME exerts its tumor-promoting function in part by increasing the cancer cell’s motility, hence possibly enhancing its metastatic abilities." (PMID 30602372, 2019). "Firstly, PRAME expression shows a wide range of inter-tumor heterogeneity among patients carrying tumors of the same tissue origin, thereby limiting the overall response rate." (PMID 31311081, 2019). "We discussed some of the major challenges for PRAME-based immunotherapy that need to be addressed, including the intra- and inter-tumor heterogeneous expression of PRAME and the potential role of PRAME in the upregulation of immune evasion mechanisms." (PMID 31311081, 2019). "Using both techniques, we found that silencing of PRAME reduced tumor cell migration by an average of 40%, while overexpression of PRAME increased the migratory potential of TNBC cells by an average of 60%." (PMID 30602372, 2019). "In line with its roles in inhibiting cancer cell growth and invasion, knockdown of PRAME dramatically reduced the expression of E-cadherin, an important gene known to suppress tumor progression." (PMID 27391090, 2016). "Across all samples, larger tumor size was the only clinical feature that correlated with PRAME+ status, suggesting that PRAME becomes transcriptionally activated later during tumor progression." (PMID 27486988, 2016). "Expression of PRAME in malignant cells is known to be subject to epigenetic regulation, as we and others have shown that DNA demethylating agents can induce PRAME in tumours and leukemic cell lines." (PMID 23460923, 2013). "This antigen is expressed in varying cancer types and PRAME expression in tumor cells has an impact on prognosis and survival of cancer patients." (PMID 23409080, 2013).
tumor (continued). "We confirmed the tumor-exclusive expression pattern of PRAME by showing that PRAME mRNA was detected in AML and ALL cell lines as well as in bone marrow from AML patients but not in bone marrow or peripheral blood from healthy donors." (PMID 23940586, 2013). "PRAME has been reported to be epigenetically regulated by the DNA methylation mechanism, and hypomethylating agents including decitabine and azacitidine upregulate PRAME expression in a variety of tumor cells." (PMID 23940586, 2013). "DNA microarray data from micro-dissected HL cells indicate expression of PRAME in a large proportion of the tumor cells." (PMID 23409080, 2013). "PRAME is synonymous with MAPE (melanoma antigen preferentially expressed in tumours) and OIP4 (OPA-interacting protein 4), and its expression profile defines it as a cancer-testis antigen." (PMID 20799951, 2010). "Examples include the MAGE, BAGE, GAGE and MAPE/PRAME protein families, all of which have been detected in tumours of many different histological types." (PMID 20799951, 2010). "The proteins CLU, ITGB3, CAPG, and PRAME were examined with western blot for semiquantitative measurements of each protein in 98 tumours." (PMID 19775429, 2009). "The expression of CLU, ITGB3, CAPG, and PRAME was investigated to study differences in expression levels between tumours from survivors and tumours from deceased patients." (PMID 19775429, 2009). "In our previous studies, PRAME was detected as more expressed in tumours from deceased patients compared to tumours from survivors." (PMID 19775429, 2009). "Allelic expression imbalance was also common (16 out of 18 samples) in tumours that expressed PRAME." (PMID 16222316, 2005). "Additionally, 42% of PRAME-positive patients showed molecular responses through circulating tumor DNA analysis, indicating biologic activity of the treatment." (PMID 40868240, 2025). "PRAME is a cancer-testis antigen involved in the regulation of tumor-specific immune responses." (PMID 40225093, 2025). "PRAME showed focal or patchy, weak nuclear staining in all tumours." (PMID 39268598, 2025). "EIF1AX mutations were associated with Class 1 tumors (p < 0.0001), PRAME(-) status (p < 0.0001), decreased tumor diameter (p < 0.0001), lack of ciliary body involvement (p < 0.0001), and male sex (p < 0.0001)." (PMID 41387680, 2025). "PRAME expression in numerous neoplasms and its clinical relevance." (PMID 40868240, 2025). "Taken together, these findings highlight that the prognostic significance of PRAME may vary depending on tumor context and subtype." (PMID 40868240, 2025). "In addition, IMC-F106C was tested against a wide range of primary normal cells from 10 tissue types and 29 different cell types, including cells of skin and lung origin, to further confirm specificity against PRAME+ tumor cells." (PMID 39659431, 2024). "To examine whether PRAME-directed TCR-based immunotherapy could be used to treat distinct tumor subsets, we first carried out bioinformatics analysis using TCGA." (PMID 39659431, 2024). "However, there is a range of PRAME expression among tumor cell lines and primary tumor specimens that can affect the level of ImmTAC®-mediated responses." (PMID 39659431, 2024). "Additionally, many studies propose that PRAME expression in tumour cells renders these cells resistant to normal target therapies." (PMID 38338862, 2024). "In all tumor categories, PRAME expression correlated with increased histone 3 acetylation." (PMID 38541782, 2024). "Given the role of PRAME in gametogenesis, its increased expression is thought to promote tumorigenesis through inhibition of retinoic acid signaling, promotion of epithelial to mesenchymal transition, and promotion of a pro-tumor microenvironment." (PMID 39451258, 2024). "PRAME has also been found to be expressed by various types of neoplasms." (PMID 37796789, 2023).